BRAF (B-Raf proto-oncogene, serine/threonine kinase)
Diseases named in the same sentence as BRAF in open-access papers (continued):
Sharing a sentence is not in itself a finding about the gene and the disease.
melanoma (continued). "Upregulation of the receptor tyrosine kinase AXL has been also linked with both a reduced response to immune checkpoint blockade as well as the development of therapy resistance to BRAF directed therapies in melanoma." (PMID 35008245, 2021). "The presence of DNTs has been demonstrated within lymph node metastases of melanoma in the shape of tolerogenic T cells, and their accretion has been described in a serial biopsy of melanoma metastases in patients treated with BRAF and MEK inhibitors." (PMID 33669266, 2021). "The development of small-molecule inhibitorstargeting RAF proteinkinases has driven advances in biomedical research and delivered drugsfor the treatment of mutant BRAF-driven melanomas, which have improvedpatient outcomes." (PMID 33750116, 2021). "To identify new drug candidates against melanoma, we investigated the molecular mechanism of action of the Octopus Kaurna-derived peptide, Octpep-1, in human BRAF(V600E) melanoma cells using proteomics and RNAseq coupled with metabolic analysis." (PMID 33672955, 2021). "Mutations cooperation between NF1 and BRAF was also described in melanocytic nevi to explain the bypass of oncogene-induced senescence (OIS) and the progression to transformed melanoma." (PMID 34362135, 2021). "This screen identified eight out of the 32 small molecule inhibitors that effectively inhibited the survival of multiple BRAF mutant melanoma cell lines." (PMID 34771678, 2021). "We hypothesized that a low dose of the BRAF-inhibitor dabrafenib can mitigate the skin toxicity associated with a full dose of the MEK-inhibitor trametinib in patients with advanced NRASQ61R/K/L mutant melanoma who progressed after treatment with immune checkpoint inhibitors." (PMID 33921947, 2021). "We obtained the mutation status of BRAF, NRAS and NF1 for the melanoma samples from the TCGA database." (PMID 34698264, 2021). "In this study, with the use of untargeted metabolomics and phenotype microarrays, we characterize the metabolic profiles of melanoma persister cells mediated by treatment with vemurafenib, a BRAF inhibitor." (PMID 34822435, 2021). "Altogether, these findings demonstrate that the ERK1/2-MNK1 axis is critical to bilirubin-induced blockage of vemurafenib in BRAF V600 mutant melanoma cells." (PMID 34222023, 2021). "Here we describe some of the main molecular mechanisms underlying the resistance to mutated BRAF and NRAS genes in melanomas." (PMID 34063141, 2021). "Nonetheless, acquired resistance to the clinically approved MAPK pathway-targeting drugs for melanoma, BRAF and mitogen-activated protein kinase kinase (MEK) inhibitors, have been frequently reported." (PMID 33916029, 2021). "As an example of copy number normalization, BRAF gene in melanoma FFPE12 sample underwent both copy number variation (CNV) and mutation; VAF for BRAF V600K mutation was consistent with ddPCR after normalizing the copy number of BRAF gene." (PMID 34675197, 2021). "High expression of GPNMB promotes tumor migration and invasion by interacting with integrins to localize immune-suppressive and pro-angiogenic cells to the tumor and renders melanoma resistant to BRAF and MEK inhibitors." (PMID 34570764, 2021). "At the same time, it was shown that BRAF-mutant melanoma cells, which were sensitive to BRAF inhibitors, presented higher glycolytic, bioenergetic and phospholipid metabolic activity compared to resistant cells." (PMID 33730175, 2021). "Here, we scrutinized the impact of BRAF/MEK inhibition on adaptive immune responses in melanoma patients by performing a comprehensive immunological characterization in sequential tumor biopsies obtained before and during BRAF/MEK inhibition." (PMID 33275172, 2021). "Currently two BRAF inhibitors are approved for clinical use, vemurafenib and dabrafenib, targeted at melanoma." (PMID 33094325, 2021).
melanoma (continued). "The construction of the logical model aims at summarizing the current molecular understanding of BRAF gene and its molecular partners in both colorectal cancers and melanomas." (PMID 33507915, 2021). "Our study showed that VERU-111bears inspiring potential in synergistically combination with BRAF inhibitor Vem to overcome drug resistance in melanoma." (PMID 33841154, 2021). "Herein, we present the first case of anti-MUSK (+) MG in a woman with metastatic BRAF-mutant melanoma after long-term treatment with dabrafenib (BRAF inhibitor) and trametinib (MEK inhibitor)." (PMID 34722270, 2021). "Interaction of total RPS3 with HNRNPU showed a decrease in the cytoplasmic fraction of NRAS mutant melanoma cells treated with MEKi and in BRAF mutant cells treated with combination mBRAFi/MEKi as assessed by PLA analysis." (PMID 34070332, 2021). "Using BRAF mutant melanoma cell models, we demonstrate that although CDK4/6 inhibition does not alter the metabolic phenotype following BRAF/MEK inhibition, CDK4/6 inhibition alone significantly enhances mitochondrial metabolism." (PMID 33572972, 2021). "A multi-center, international, open-label safety study enrolled 3226 patients with advanced metastatic BRAF V600 melanoma and investigated vemurafenib’s effectiveness." (PMID 34066301, 2021). "Understanding the role of BRAF mutant clones in melanoma resistance to BRAF inhibition is key to conduct rational drug development in this field." (PMID 34853302, 2021). "Patients with unresectable stage IIIc–IV, BRAF V600E mutant melanoma were randomly assigned 1:1 to 28-day cycles of vemurafenib (960 mg b.i.d.), and cobimetinib (60 mg/d for 21 days) with either atezolizumab (840 mg) or placebo." (PMID 34743688, 2021). "One study found that 20% of melanoma patients after initiation of BRAF-inhibitor therapy developed two or more resistance mechanisms." (PMID 35008286, 2021). "BRAF and MAPK are others important signaling pathways particularly implicated in the progression of melanoma and thyroid cancer." (PMID 34439194, 2021). "We demonstrate that IGF1R and IR are activated in response to chronic dabrafenib and trametinib resistance in BRAF-mutant melanoma and are differentially expressed in parental and resistant cell lines." (PMID 34831014, 2021). "BRAF-mutant melanoma patients have benefited from BRAF kinase and MEK kinase inhibitor-based therapies (vemurafenib, dabrafenib, and trametinib)." (PMID 33766731, 2021). "Using The Cancer Genome Atlas (TCGA) dataset of skin cancers, we analyzed isomiR expression in primary melanoma and melanoma metastasis and tested their association with NF1, BRAF and NRAS mutations." (PMID 34698264, 2021). "Since an EMT switch is partly regulated by the BRAF/MEK signaling pathway in normal melanocytes, BRAF/MEK inhibitors induce the opposite reprogramming in melanoma." (PMID 34683910, 2021). "Hyperactivation of MAPK signaling in BRAFV600E-mutant melanoma cells leads to increased c-Jun expression, resulting in mesenchymal-like phenotype and resistance to BRAF/MEK inhibitors (MAPKi)." (PMID 34604096, 2021). "In this paper, we first carried out functional studies in melanoma cell lines to investigate the molecular role of miR-181a/b in melanoma, also raising evidence of their involvement in resistance to BRAF inhibitors-resistance in vitro and in clinical samples." (PMID 33670365, 2021). "As such, therapies targeting BRAF and MEK has significantly impacted the natural history and outcome of patients with BRAF mutant melanoma, even in those with CNS metastases." (PMID 35096602, 2021). "An important consideration is that the CNMR collected data from December 2011 and the most important drug in the field of melanoma, like BRAF inhibitors, anti-CTLA4, anti-PD-1 were approved in the following years." (PMID 34307142, 2021). "The knockout of this tumor suppressor gene in BRAF mutant melanoma cells triggered senescence and apoptosis through overactivation of the EGFR‐MAPK pathway." (PMID 33955157, 2021).
melanoma (continued). "As observed in tumors from melanoma cells sensitive to BRAF inhibitor, CRO15 induced a strong increase in LC3, active caspase 3 and TUNEL staining compared to tumor sections from control or PLX4032." (PMID 33431809, 2021). "Supporting studies from BRAF mutant melanoma have shown that combined BRAF-MEK inhibition is effective, exhibiting synergistic growth suppression and delaying onset of resistance, and has been clinically approved for this cancer type." (PMID 34805167, 2021). "Recent clinical studies have shown that BRAF kinase inhibitors, such as acetinib and plx4032, have been used in the treatment of malignant melanoma." (PMID 33622273, 2021). "Herein we report six pyrimido[4,5-d]pyrimidin-2-one derivatives possessing highly potent anti-proliferative activities on melanoma cells harboring BRAF class I/II/III mutants." (PMID 33917428, 2021). "Increased nuclear accumulation of YAP/TAZ leads to actin remodeling, which in turn confers BRAF inhibitor resistance in BRAFV600E-mutant melanoma cells." (PMID 34604096, 2021). "We tested the RAS–RICTOR interaction using PLA in situ in melanoma sections obtained from five patients before targeted treatments with BRAF and MEK inhibitors and when resistance occurred." (PMID 34680615, 2021). "In melanoma, BRAF‐V600E‐induced ER stress can be mediated by the sequestration of ER chaperone GRP78 or the activation of p38." (PMID 34355491, 2021). "The preferred contemporary path for treating advanced melanoma patients is utilizing an amalgamation of medicines that impede the kinase actions of BRAF and anti-MEK." (PMID 35003391, 2021). "In melanoma cell lines MITF amplification is commonly accompanied by CDKN2A inactivation and BRAF mutation." (PMID 33556121, 2021). "Some studies support the notion that MEK/ERK inhibitor treatment in BRAF-mutant melanoma promotes the stromal microenvironment of melanoma cells toward a more fibrotic phenotype." (PMID 34063141, 2021). "Further experiments found that a drug called barasertib is able to inhibit the growth of melanoma cells with the mutant form of BRAF." (PMID 34812139, 2021). "MCL-1 depletion significantly induced apoptosis in melanoma cells and resensitized mutant BRAF melanoma cells to anoikis compared with depletion of BCL-2 or BCL-xL." (PMID 33883020, 2021). "In some melanoma cell lines driven by BRAF fusions with a 5′ partner that contains a dimerisation domain, PLX8394 has been shown to paradoxically activate RAF signalling." (PMID 33367512, 2021). "In July 2020, FDA approved the immunotherapy drug Atezolizumab for combined use with the MEK inhibitor Cobimetinib and RAF inhibitor Vemurafenib in BRAF-mutant melanomas." (PMID 34461089, 2021). "In summary, our metabolic analyses have revealed that inhibition of CDK4/6 upregulates mitochondrial function in BRAF mutant melanoma cells." (PMID 33572972, 2021). "BRaf mutations have also been shown to reduce CD8+ T-cell tumor recognition and induce internalization of major-histocompatibility complex molecules in melanoma tumor cells." (PMID 34680208, 2021). "Dose response of a panel of melanoma cell lines to G9, showed that BRAF mutant melanoma cells were sensitive to G9, and the degree of sensitivity correlated with Usp9x and SOX2 expression." (PMID 33613844, 2021). "Nivolumab/ipilimumab in stage IV malignant melanoma was associated with the highest RFS benefit (HR 0.23; 97.5% CI= 0.12-0.45), followed by dabrafenib/trametinib in stage III BRAF-mutant melanoma (HR 0.49; 95% CI= 0.40-0.59)." (PMID 33680957, 2021). "Despite the significance of bilirubin has been gradually recognized in several diseases, the role of bilirubin in the treatment of vemurafenib in BRAF mutant melanoma is still unclear." (PMID 34222023, 2021).
melanoma (continued). "Endogenous PTEN mutations are often found in BRAF driven melanomas and at least 10% of PTEN-null BRAF melanomas show intrinsic resistance to BRAF inhibitors." (PMID 34066022, 2021). "At least one report demonstrated that patients with melanoma brain metastases treated with combination BRAF inhibitor and stereotactic radiotherapy experienced greater rates of intra-tumoral hemorrhage when compared to radiotherapy alone." (PMID 34277419, 2021). "In our work we did not identify enhancement of PD-L1 expression in vitro with palbociclib or in combination with BRAF-MEKi in our melanoma models." (PMID 34944961, 2021). "In this article, various melanoma biomarkers including BRAF, MEK, RAS, c-KIT, VEGFR, c-MET and PI3K are described, and their potential mechanisms for drug resistance are discussed." (PMID 33807778, 2021). "On this basis, it is concluded that the combination of NAMPT and BRAF inhibitors has the potential to be a new therapy for BRAFi-sensitive patients with melanoma." (PMID 34068679, 2021). "In BRAF V600E melanomas, combination treatment inhibiting BET bromodomains and either BRAF V600E or MEK kinases synergistically block cell proliferation." (PMID 34440824, 2021). "In melanoma cell lines, BRAF‐V600E was shown to induce chronic endoplasmic reticulum (ER) stress and subsequent upregulation of autophagy flux." (PMID 34355491, 2021). "We next conducted 6-color (hematoxylin, CD40, CD80, CD11c, CD8 and SOX10) multiplex IHC staining on the section of tumors from melanoma patients treated with BRAF inhibitor." (PMID 34092233, 2021). "We also observed comparable patterns for BRAF-mutant melanoma and HER2-positive breast cancer patients." (PMID 34535668, 2021). "As a result of this trial, dual agent TT has become a standard treatment option for adjuvant therapy in patients with fully resected stage III BRAF mutant melanoma." (PMID 33087895, 2021). "In the present study, we scrutinized the impact of the combined BRAF/MEK inhibition on tumor infiltrating T cells in melanoma demonstrating an increased presence of CD4+ and CD8+ T cells upon therapy." (PMID 33275172, 2021). "BRAF(V600E/K) mutation, a component of the mitogen-activated protein kinase (MAPK) pathway, is regarded as a significant oncogene in melanoma." (PMID 33868987, 2021). "The use of BRAF inhibitors develops a stress response—autophagy as a mechanism of drug resistance in melanoma cells." (PMID 33916175, 2021). "All three BRAF inhibitors currently in clinical phase—encorafenib, vemurafenib, and dabrafenib—have been approved to treat BRAF-mutant advanced melanoma." (PMID 33546207, 2021). "Here we performed a screen of 180 metabolic modulators for viability-reducing effects in melanoma cells in combination with the BRAF inhibitor vemurafenib." (PMID 33623106, 2021). "Recent studies have shown that CRAF can compensate for BRAF depletion via regulating DNA synthesis to remain melanoma proliferation." (PMID 33377602, 2021). "In 2011, a randomized phase 3 trial showed the superiority of the BRAF inhibitor vemurafenib over dacarbazine in OS, PFS, and ORR, and was approved for the treatment of unresectable or metastatic BRAFV600E-mutated melanoma." (PMID 33804800, 2021). "To better understand the effect of combined BRAFi and MEKi on resistance-associated mTORC1 signaling, we treated a panel of paired parental and CR BRAF mutant melanoma cell lines with PLX-4720 (PLX, 2.5 μM, BRAFi) and PD0325901 (PD, 0.25 μM, MEKi) for 24 h." (PMID 34304249, 2021). "The silencing of IGF1 re-sensitized melanoma cells to BRAF/MEK inhibition, suggesting that IGF1 plays a major role in developing drug resistance in that case." (PMID 34830951, 2021).
melanoma (continued). "In conclusion, our findings provide direct evidence and a reasonable explanation for giving a combination of a tubulin inhibitor VERU-111 with a BRAF inhibitor to overcome Vem-resistance in melanoma pateints." (PMID 33841154, 2021). "These significant clinical benefits have made combined BRAF and MEK inhibitors the new standard for advanced and metastatic V600E BRAF-mutated melanoma treatment." (PMID 33804655, 2021). "The phase 2 ImmunoCobiVem trial enrolled patients with unresectable or metastatic BRAFV600 mutant melanoma to receive BRAF/MEK inhibitor therapy with vemurafenib and cobimetinib for three months." (PMID 33804800, 2021). "Given the frequency of aberrant MAPK/ERK activity observed in melanoma, several inhibitors have been developed to target various components of this pathway, including inhibitors of BRAF, MEK and more recently RAS and ERK (reviewed in 30, 31)." (PMID 34025662, 2021). "Metastatic melanoma is frequently treated with a combination of anti-BRAF and anti-MEK tyrosine kinase inhibitors." (PMID 34575876, 2021). "Long-term treatment with BRAF inhibitors such as vemurafenib triggers the selection of resistant melanoma cells that, as a consequence of a mitochondrial respiration phenotype, exhibit increased ROS production and increased redox response." (PMID 34830947, 2021). "The frequency of NF1 mutations in melanomas is approximately 15%, with a higher frequency observed in older patients, chronic sun damage lesions, desmoplastic melanomas, and BRAF/NRAS wild-type melanomas (a frequency of 70%)." (PMID 34831002, 2021). "The US National Comprehensive Cancer Network recommends both immunotherapy and targeted therapy as first-line treatments for unresectable melanoma; however, targeted therapy is preferred for rapidly deteriorating BRAF-positive melanomas." (PMID 34914610, 2021). "The BRAF inhibitors (BRAFi) vemurafenib and dabrafenib were approved for use as single agents in patients with BRAF-mutant melanoma." (PMID 35187538, 2021). "The same recommendation is valid for BRAF-mutant advanced melanoma including an additional option with BRAF/MEK inhibitors." (PMID 33804800, 2021). "In this study, subcutaneously injected mice with BRAFV600E mutant melanoma cells were treated with BRAF inhibitor dabrafenib." (PMID 33535416, 2021). "BRAF V600E mutations occur in various cancers, such as melanoma, non-small-cell lung cancer, breast cancer and CRC, and inhibitors targeting BRAF have demonstrated clinical benefit for these patients." (PMID 34663410, 2021). "In this study, we further explored the role of miRNAs in melanoma resistance to BRAF inhibitors (BRAFi)." (PMID 33670365, 2021). "These BRAF inhibitors (vemurafenib, dabrafenib, and encorafenib) are specific for the treatment of patients with unresectable BRAF V600E/K/D mutant melanoma." (PMID 34829820, 2021). "Dabrafenib and vemurafenib are specific to BRAF V600E/K mutation and were approved by the US Food and Drug Administration (FDA) for use in melanoma." (PMID 34116682, 2021). "This is important given the critical role of the PI3K pathway in promoting senescence bypass in fibroblasts, as well as in melanoma, where loss of PTEN can cooperate with activated BRAF or NRAS to promote tumor initiation and metastatic dissemination." (PMID 34819350, 2021). "To date, all 3 combinations have been approved as first-line treatments for BRAF-positive advanced melanoma, especially in rapidly deteriorating cases." (PMID 34914610, 2021). "In fact, it must be stressed that there is a higher trend of BRAF V600-mutant melanoma, with respect to BRAF wild-type ones, to involve the brain and liver as a first site of metastasis, thus affecting negatively the prognosis of these patients." (PMID 33801689, 2021).